VIM (vimentin)
Diseases named in the same sentence as VIM in open-access papers (continued):
Sharing a sentence is not in itself a finding about the gene and the disease.
breast carcinoma (continued). "A study that examined SCRIBBLE protein expression using immunohistochemistry in histologic breast cancer samples confirmed the complex influence of SCRIBBLE on the prognosis of breast cancer, which depends on ER status and vimentin expression." (PMID 36675340, 2023). "In this study, breast cancer cells treated with anti-PADI4 antibodies showed decreased expression of EMT-related proteins, including vimentin, claudin-1, and N-cadherin." (PMID 37804426, 2023). "Accordingly, in clinical specimen of breast cancer patients, the specific EMT markers, such as Vimentin, Zeb1, Twist1, β-catenin, and MMP9 showed opposite expression patterns between the CD44+CD24− phenotype and the ALDH+ phenotype." (PMID 36768876, 2023). "Potential therapeutic inbreast cancer by regulating breast cancer-related genes,including SERPINE1, PGAP3, MAP3K1, MAPK1, GSTO2, VIM, SPARC, and FGF2." (PMID 37191432, 2023). "In a second example, a breast cancer FFPE tissue sample was imaged by fluorescence microscopy and MALDI-IHC using a panel of 5 MiralysTM probes consisting of vimentin, collagen, HER2, histone H2A.X (dual-labeled) and Na+/K+ ATPase (dual-labeled) antibodies." (PMID 37201132, 2023). "Results show that compared with normal tissue, the expression of VIMENTIN, α-SMA and CD31 in breast cancer tissues were significantly increased." (PMID 37283769, 2023). "Initially, we defined the EMT status of the four breast cancer cell lines based on morphological aspects, EMT-marker (E-cadherin, CDH1 and Vimentin, VIM) expression and migratory behavior." (PMID 37175467, 2023). "In addition, the difference in the expression level of EMT markers was investigated between breast cancer stages, and we found that ZEB2 and vimentin expression was highly upregulated in the end‐stage BC patients compared with early‐stage of cancer." (PMID 37088469, 2023). "The proteins determined by SDS–PAGE to be expressed in mammary tissues in the rat model of DMBA-induced mammary cancer were thought to be HER-2, Nischarin, COX-2, Albumine, Vimentin, Actin, TNF-α, p16, and FABP3." (PMID 39070120, 2023). "SMRwt peptide decreased Mortalin and Vimentin protein levels and increased E-cadherin levels in MDA-MB-231 and MCF-7 breast cancer cells." (PMID 35915218, 2022). "Overall, these results suggest that the SMAD3-dependent gene signature is present in hypoxic tumors and that VIM and ITGB2 are better predictors of metastasis or cancer recurrence in lung carcinoma and breast cancer than RHOB." (PMID 35681731, 2022). "In another study, GPC3 re-expression in aggressive breast cancer cells returned mesenchymal-like breast cancer cells to an epithelial phenotype as shown by the suppression of Snail, ZEB1, vimentin, and increased expression of E-cadherin." (PMID 36358747, 2022). "In human breast cancer cells, miR-146b overexpression significantly inhibits cell proliferation and EMT by upregulating E-cadherin and downregulating vimentin expression, modulating the transcription of the EMT-related genes." (PMID 36359024, 2022). "In a study conducted on patients with breast cancer, a correlation was observed between ER−α and two typical EMT markers, MMP9 and vimentin." (PMID 36232636, 2022). "In xenograft in vivo models, luteolin inhibited lung metastases of breast cancer and the expression of EMT molecules Vimentin and Slug in primary tumor tissues." (PMID 35056792, 2022). "Extracellular vesicles of insulin-like growth factor-1 (IGF-1), which is a crucial regulatory factor of mammary glands, promote the downregulation of CDH1 and upregulation of vimentin, N-cadherin, and MMP-9 in MDA-MB-231 breast cancer cells." (PMID 35464064, 2022). "Upregulation of Vimentin (VIM), alpha-Tubulin (TUB) and Detyrosinated tubulin (GLU) in circulating tumor cells (CTCs) derived from breast cancer patients is related to poor prognosis." (PMID 35207643, 2022).
breast carcinoma (continued). "The expression of Vimentin is significantly elevated in NHW patients relative to NHB patients, and NHW relative to NHB and H/L breast cancer patients." (PMID 36494865, 2022). "Breast cancer cells HTB-26 constitutively co-expressed keratins and vimentin and oriented along PCL fibers and proliferated in vitro." (PMID 35877331, 2022). "TCGA database analysis showed that E-Cadherin was reduced and Vimentin and SNAIL were elevated in eMDSCshigh breast cancer patients relative to eMDSCslow group." (PMID 36329699, 2022). "Western blot and immunofluorescence analyses were also done to identify the expression levels of E-Cadherin, Vimentin and SNAIL in luminal A breast cancer cell lines after being co-cultured with eMDSCs." (PMID 36329699, 2022). "Meanwhile, we found that E-cadherin was increased, while N-cadherin, Vimentin and Fibronectin were decreased at the transcriptional level and protein level in MDA-MB-231-shDNMT1 breast cancer cells." (PMID 36273188, 2022). "In conclusion, WF promotes the proliferation, EMT markers (E-cadherin and Vimentin), and CSC markers (CD44high/CD24low) of MDAMB-231 and Sum-149 breast cancer cells." (PMID 35735628, 2022). "For instance, the inhibition of DLX6-AS1 was reported to increase the protein level of E-cadherin and decrease vimentin expression, thus repressing the EMT process in breast cancer cells." (PMID 36613528, 2022). "Ethanol-based garlic extract prevents breast cancer evolution driven by a hypoxia-induced decrease in CDH1 and increased vimentin and motility." (PMID 35464064, 2022). "Otherwise, SOX21-AS1 silencing in MCF7 and BT-20 cells repressed vimentin and N-cadherin expression, while its overexpression displayed the opposite effect, which indicates its promoting role in EMT progression in breast cancer." (PMID 36613528, 2022). "CAF-educated monocytes can increase the motility and invasiveness of breast cancer cells and the expression of epithelial-mesenchymal transition (EMT)-related genes and vimentin proteins, eventually exerting their immunosuppressive role in breast cancer." (PMID 35464435, 2022). "We next planned to study the role of EndMT in angiogenesis of breast cancer, then we performed double-IHC staining for EndMT markers (α-SMA, FSP-1, Vimentin, VE-Cadherin and Fibronectin), and MVD (CD34, vWF) on IDC samples." (PMID 36465358, 2022). "In miR-374a-transduced breast cancer cell lines, epithelial markers including E-cadherin, γ-catenin, and CK18 were drastically downregulated, while mesenchymal markers such as vimentin and N-cadherin were upregulated." (PMID 33477629, 2021). "It has been reported earlier that curcumin blocked the lipopolysaccharide-induced EMT procedures through the modulation of the expression of motility and invasiveness marker, e.g., vimentin and E-cadherin, in MDA-MB-231 breast cancer cells." (PMID 34298639, 2021). "It has been reported that there were significant DOK7, VIM, and CXCR4 hypo methylations in a sub population of Iranian breast cancer cases compared with normal subjects." (PMID 33883026, 2021). "In this study, we observed a decreased E-cadherin expression and an increased Vimentin and N-cadherin expression after transfection with miR-381-3p mimics, suggesting that miR-381-3p inhibits the EMT phenotype in breast cancer." (PMID 34362391, 2021). "We also observed a notable inhibition of EMT markers–vimentin and matrix metalloproteinase 9 (MMP-9) that play a crucial role in breast cancer metastasis with ATQ treatment." (PMID 34071408, 2021). "In breast cancer, ARPC2 expression significantly upregulated the expression of vimentin, N-cadherin, MMP-9, ZEB1, and MMP-3, activated the TGF-β pathway, and eventually led to epithelial–mesenchymal transition (EMT)." (PMID 34307456, 2021). "Other breast cancer decellularized scaffolds also showed an inverse correlation between EMT and differentiation markers, with an increased expression of VIM, ZEB1 and SNAIL paralleled with a decreased E‐cadherin." (PMID 33368325, 2021).
breast carcinoma (continued). "First, in MCF-7 breast cancer cells treated with I3C and ICZ, E-cadherin mRNA expression was increased while vimentin mRNA expression was attenuated." (PMID 34572548, 2021). "The results showed that compared with the normal breast cancer cells, the expression of E-cadherin in the lncRNA TPA overexpression cells was reduced, and the expression of Fibronectin, TGF-β1 and Vimentin were significantly increased." (PMID 34422811, 2021). "Our results revealed that ATQ reduced the constitutive expression of vimentin and MMP-9 suggesting ATQ inhibits metastatic markers in breast cancer." (PMID 34071408, 2021). "Altogether, studies suggest that in breast cancer, SALL1 and SALL4 are involved in migration, invasion, and EMT by regulating common targets such as E-cadherin and vimentin, but in an opposite manner." (PMID 34944911, 2021). "Calycosin treatment downregulated expression levels of EMT- and metastasis-related proteins such as N-cadherin, Vimentin, CD147, MMP-2, and MMP-9 levels in breast cancer cells." (PMID 34096887, 2021). "Genes related to proliferation (MKI67, CCNA2), differentiation (EPCAM, CDH1), epithelial to mesenchymal transition (VIM, SNAI2), pluripotency and breast cancer stem cells (SOX2, NANOG, CD44) were included." (PMID 34090457, 2021). "The stromal cell derived leptin is reported to support cancer metastasis in estrogen receptor positive and triple negative breast cancer cells by enhancing EMT via upregulating SERPINE 1, IL-6, MMP-2, SNAI 2, TWIST 1, vimentin and downregulating E-cadherin." (PMID 34588926, 2021). "These include human cell lines A549 vimentin red fluorescent protein (epithelial cell line), HCT116 vimentin RFP (colorectal cancer), BT-474 E-cadherin EmGFP (breast cancer), and MCF10A E-cadherin EmGFP (breast epithelial cells)." (PMID 33948525, 2021). "Depending on the expression of EpCAM, CK7, Snail, N-cadherin, and Vimentin, we considered the probability of 24 CTC phenotypes in breast cancer patients." (PMID 33801519, 2021). "A similar positive correlation between vimentin and AXL expression was observed in breast cancer patients as well as in 92 breast cancer cell lines." (PMID 34638469, 2021). "Induction of EMT in the breast cancer cell line, MCF10A, by Slug and the oncogenic H-Ras, induces vimentin overexpression, which in turn leads to AXL expression and activation." (PMID 34638469, 2021). "Compared with the normal breast cancer cells, the expression of E-cadherin protein in the lncRNA TPA knockdown cells was significantly increased (p < 0.01), and the protein expression of Vimentin, fibronectin and TGF-β1 was significantly reduced (p < 0.01)." (PMID 34422811, 2021). "Conversely, TGFβ1 treatment decreased E-cadherin levels and increased N-cadherin, Vimentin, CD147, MMP2 and MMP9 expression levels in the breast cancer cells." (PMID 34096887, 2021). "HTyr treatment in different breast cancer cell lines decreased, in fact, β-catenin and cyclin D1 protein expression and reduced the expression of EMT markers such as Snail and vimentin." (PMID 33513799, 2021). "Here we report that the expression of CMTM6 positively correlates with the epithelial to mesenchymal transition (EMT) score in breast cancer cell lines and with the major EMT marker Vimentin in triple-negative breast cancers (TNBC)." (PMID 33803139, 2021). "For example, in breast cancer stem cells, the CD24-CD44+ signature is related to a mesenchymal state with higher vimentin expression while the ALDH+ signature corresponds to an epithelial state of the cancer stem cells." (PMID 34638469, 2021). "Compared with SEN-CM-MCF-7-mRFP, adjacent breast cancer cells co-cultured with SEN-MCF-7 cells (Co-MCF-7-mRFP) exhibited more significant downregulation of E-cadherin and upregulation of Vimentin." (PMID 33467780, 2021).
breast carcinoma (continued). "Western blotting was used to detect the expression of E-cadherin, N-cadherin, vimentin, MMP2 and MMP14 in different functional models of breast cancer subtypes to verify the occurrence of EMT." (PMID 33591943, 2021). "In human breast cancer cells (MDA-MB-458 cells), EGF induced a calcium transient that was accompanied by increased vimentin expression, which is suggestive of EMT." (PMID 34360952, 2021). "The mesenchymal MDA-MB-231 breast cancer cell line had lower mRNA expression of epithelial marker CDH1 and higher expression of mesenchymal markers VIM and ZEB1 compared to the MCF-7 and MDA-MB-468 cell lines." (PMID 34207708, 2021). "77% (13 out of 17) of p18mt;Gata3+/- mammary tumors were positive for EMT markers including fibronectin (Fn), vimentin (Vim), CD29, and EMT-TFs in 2-60% of the tumor cells." (PMID 34373738, 2021). "The results of immunohistochemical staining indicated downregulation of E-cadherin and upregulation of vimentin in stress group compared with control group, which confirmed the development of EMT in 4T1 breast cancer cells." (PMID 32934214, 2020). "Resistin also accelerates invasion and migration of breast cancer cells via stimulating ezrin, radixin, and moesin (ERM) complex, then activated ERM upregulates expression of vimentin, an EMT marker." (PMID 33123472, 2020). "STAT3 signaling pathway plays a crucial role in proliferation (Bcl-2, Survivin), angiogenesis (HIF1α, VEGF), and epithelial-mesenchymal transition (Vimentin, MMP-9) in breast cancer cells and has been validated as a drug target for cancer therapy." (PMID 31948057, 2020). "In this investigation, we analyzed the effect of EA on E-cadherin, β-catenin, vimentin, and fascin expression patterns in HER2-positive breast cancer cell lines." (PMID 32947764, 2020). "In the present study, three EMT-related proteins E-cad, N-cad, and vimentin and two proteolytic enzymes MMP-2 and MMP-9 were selected as targets to investigate the influence of SA in the indicated breast cancer cells." (PMID 33381039, 2020). "The basal breast cancer cell line FOXC2 was found to delocalize E-cadherin into the cytosol, induce N-cadherin, vimentin, fibronectin, αSMA and to regulate canonical TGF-β signaling." (PMID 32998363, 2020). "In conclusion, in our study, we demonstrate that Musashi protein knockdown downregulates several important stem cell characteristics in breast cancer, including CD44, vimentin and GBX2, likely due to Notch pathway downregulation." (PMID 32245259, 2020). "In conclusion, S100P enhances the proliferation, adhesion, migration, and invasion of breast cancer cells through the regulation of NF-κB, CCND1, E-cadherin and Vimentin." (PMID 33042844, 2020). "EMAT clusters displayed distinct expression profiles for CDH1, VIM, RHOA, and JUP, well-accepted biomarkers of epithelial (E), mesenchymal (M), amoeboid (A), and collective cell migration in breast cancer, respectively." (PMID 32641077, 2020). "By immunohistochemistry, TF expression was more particularly shown to correlate with vimentin expression in in vitro models of EMT, in human breast cancers and in CTCs isolated from metastatic breast cancer patients." (PMID 32152404, 2020). "A linear regression analysis revealed a negative correlation between SIPA1 and E-cadherin expression in breast cancer tissues (*P<0.001) and a positive correlation between SIPA1 and vimentin expression (*P<0.001)." (PMID 32193333, 2020). "The mesenchymal marker vimentin and epithelial marker E-cadherin were assessed to evaluate EMT in breast cancer cells." (PMID 32836215, 2020). "Examination of the expression of EMT markers indicated that emodin significantly attenuated TAM-like macrophage-induced N-cadherin, Vimentin and MMP expression in breast cancer cells." (PMID 32724475, 2020).
breast carcinoma (continued). "A recent report showed that LEF1 and multidrug resistance-related genes, such as ABCG2, VIM, and Cav1, are highly increased in docetaxel (DTX)-resistant MCF7 breast cancer cells, indicating that LEF1 is involved in multidrug resistance in cancer." (PMID 32933177, 2020). "A correlation was seen between the mesenchymal marker vimentin and AXL in both migratory cells at the wound edge in cell-based assays as well as in mammary tumors." (PMID 32148495, 2020). "Immunofluorescence staining showed increased β-catenin and reduced Vimentin in SNX27-KD injected mice, compared to that in WT MDA-MB-231 breast cancer cells." (PMID 31182056, 2019). "Whereas in GTN-treated spheroid breast cancer MDA-MB-231 cells, EMT markers such as vimentin and N-cadherins were significantly downregulated, but the expression of E-cadherin was enhanced when compared to adherent breast cancer cells." (PMID 31416203, 2019). "In our RR model we demonstrated a down regulation of E-cadherin and upregulation of vimentin, N-cadherin and SNAIL, all known biomarkers for EMT in breast cancer, in the MCF-7 RR and ZR-751 RR cell lines." (PMID 30987655, 2019). "Conversely, Hsp90AA1 overexpression upregulated vimentin and downregulated E-cadherin and occludin, suggesting that Hsp90 plays a vital role in EMT in breast cancer." (PMID 31921692, 2019). "We here show that Vimentin, SNAIL and cell proliferation decreased by MTF treatment in breast cancer cells with a mesenchymal phenotype, although these particular cells required higher doses of MTF to provoke an inhibitory effect." (PMID 31337349, 2019). "The loss of E-cadherin and increased expression of mesenchymal markers (N-cadherin, Snail, Twist, Vimentin, and Zeb1) were used as EMT indicators in breast cancer cells." (PMID 31889895, 2019). "To find out possible mechanism behind reduction in the metastatic potential of CRAd treated breast cancer cells, we performed RT-PCR and western blot analysis of three EMT-markers (E-cadherin, N-cadherin and Vimentin)." (PMID 31097752, 2019). "Previous studies demonstrated that BLBC cell lines expressed EMT-acquired markers such as Snail, vimentin, and N-cadherin, but lost EMT-attenuated marker E-cadherin compared to luminal breast cancer cell lines." (PMID 31462314, 2019). "Mesenchymal markers, such as vimentin, moesin, and receptor tyrosine kinase Axl, are highly expressed in TNBC basal B subtype of breast cancer cells, and vimentin and Axl proteins were expressed in a subset of human TNBC tumors from patients." (PMID 30777098, 2019). "The co-expression network revealed that ELAVL2, VIM, MRPS12, HSPE1, EZH2, HIST1H4B, and MRPL13 played a vital role in the progression of breast cancer, and we further selected important modules of target genes through MCODE." (PMID 30881302, 2019). "The positive expression of vimentin, a marker of epithelial-to-mesenchymal transition (EMT) and basal-like breast cancer suggested that tumor cells have undergone EMT." (PMID 31698751, 2019). "Currently, IHC tests are performed on most patientswith breast cancer referring to laboratories in order totest for ER, PR, E-cadherin, CK5/6, vimentin and Ki67,among which HER-2 gene amplification is examinedto prescribe and use Herceptin." (PMID 31210439, 2019). "The low expression of HSD17B11 and ITGA2 and the high expression of VIM and ABHD17C have all been validated by recent sequencing studies on breast cancer, reflecting the accuracy of these two rules." (PMID 31456818, 2019). "These transcription factors, which regulate expression of Vimentin and SNAIL, increased in cultured primary breast cancer cells in response to IL-6." (PMID 31337349, 2019). "In order to determine the variation, we have compared the level of general breast cancer markers (MGB1, HER2) and genes used for CTCs-EBF classification into EMT phenotypes (CK19, CDH1, VIM, CDH2, PLS3)." (PMID 30634453, 2019).